JUN (Jun proto-oncogene, AP-1 transcription factor subunit)
Diseases named in the same sentence as JUN in open-access papers (continued):
Sharing a sentence is not in itself a finding about the gene and the disease.
diabetes (26 papers, 2010 to 2025). "The JUN-Laetiposide G complex exhibited strong hydrogen bonding and van der Waals interactions, suggesting its potential to modulate JUN-related signaling in diabetes." (PMID 40508014, 2025). "Among these, seven key targets (JUN, AKT1, ESR1, CASP33, TNF, SRC, and IL6) were found to have the highest network connectivity, indicating their central role in treating diabetes with Chaga." (PMID 40508014, 2025). "Key targets such as JUN, AKT1, ESR1, CASP3, TNF, SRC, and IL6 were identified as central regulators in diabetes-related pathways, with molecular docking confirming strong binding interactions between Chaga-derived phytochemicals and these targets." (PMID 40508014, 2025). "RELA, JUN, and PTGS2 mediate inflammatory pathways that ultimately drive insulin resistance, diabetes, and its complications." (PMID 39458839, 2024). "The results offer us a comprehensive understanding of the therapeutic effects of previously identified target proteins, including AKT1, IL6, PPARG, JUN, CASP3, EGFR, and PTGS2, in the context of diabetes intervention." (PMID 39707185, 2024). "A comprehensive transcriptomic analysis involving type 2 diabetes mellitus patients further revealed that miR-124-3p and miR-16-5p affect the expression of genes such as CREB1, SP1, (both TFs in our analysis) SREBF1, and JUN (hub genes)." (PMID 36232337, 2022). "Another four TFs (JUN, EGR1, NR1D1, and ATF3) (in italic) were almost involved in all the diabetes-related term and pathways." (PMID 36050744, 2022). "Our two hub genes, JUN and VEGFA, showed enrichment in the AGE-RAGE signaling pathway in diabetes complications." (PMID 36482897, 2022). "We identified 8 hub genes (JUN, ATF3, VEGFA, SLC2A1, HK2, PTGS2, PFKFB3, and KLF6) that were enriched in response to hypoxia, angiogenesis, vasculogenesis, hypoxia-induced signaling, cancer, diabetes, and transplant-related disease pathways." (PMID 36482897, 2022).
liver fibrosis (24 papers, 2012 to 2025). "Together, these findings demonstrate that hepatocyte HIF-2α acts as a critical driver of liver fibrosis by promoting hepatocyte death, associated with the attenuation of injury-mediated induction of c-JUN." (PMID 39684823, 2024). "The results further confirmed the effect of the high dose of THSW Decoction significantly increased JUN expression in the liver tissues of mice with liver fibrosis and decreased ESR1 expression." (PMID 40661312, 2025). "Our study shows abundant levels of c-JUN and its phosphorylated form in CCl4-induced liver fibrosis, which were further enhanced by the deletion of HIF-2α in hepatocytes." (PMID 39684823, 2024). "A study by Schulien et.al has shown that hepatocyte specific deletion of c-JUN mice is more prone to liver fibrosis." (PMID 39684823, 2024). "Thus, we propose that HIF-2α deletion attenuates liver fibrosis partly by inhibiting c-JUN-mediated hepatocyte survival and hypertrophy." (PMID 39684823, 2024). "JUN overexpression promotes liver fibrosis and correlates with progression from steatosis to NASH." (PMID 33785040, 2021). "Together, these data demonstrate that the hepatocyte HIF-2α regulates c-JUN phosphorylation in liver injury, and the induction of hepatocyte c-JUN in mice with disruption of hepatocyte HIF-2α could be associated with protection against CCl4-induced liver fibrosis." (PMID 39684823, 2024).
lung adenocarcinoma (23 papers, 2015 to 2025). A carcinoma that arises from the lung and is characterized by the presence of malignant glandular epithelial cells. "To further support this finding, we had tested and analyzed lung adenocarcinoma biopsy tissue samples using mixed tissue RNA sequencing and found that the JUN gene was statistically associated with successful PD-1 blockade therapy." (PMID 38874497, 2024). "Subsequently, it is verified that 9 core targets for ginseng treatment of lung adenocarcinoma, namely, JUN, IL-1β, IL-2, ICAM1, HMOX1, MMP9, MMP2, PTGS2, and TNF, are closely related to the proliferation, migration, and apoptosis of lung adenocarcinoma cells." (PMID 32802118, 2020). "Furthermore, the role of JUN discovered in this study in lung adenocarcinoma still needs more experimental validation." (PMID 38874497, 2024). "Meanwhile, according to the results of qRT-PCR, it is speculated that ginseng can treat lung adenocarcinoma by up-regulated JUN, IL-1β, IL-2, ICAM1, HMOX1, MMP9, and MMP2 targets and down-regulated PTGS2 and TNF genes." (PMID 32802118, 2020). "By integrating two time-course microarray data in human lung adenocarcinoma cells, we specifically have identified some nested gene clusters and found that TGFB1, EGR1, EGR2, EGFR, IL6, JUN, and JUNB all are involved in these clusters." (PMID 28959347, 2017). "It was thus inferred that JUN, NR3C1, and GRB2 were most likely to be new candidate lung adenocarcinoma-related genes." (PMID 26402252, 2015). "JUN and NR3C1 were detected by both differential interactions and by differential expression, increasing their possibility to be correlated with lung adenocarcinoma." (PMID 26402252, 2015). "The five largest node targets identified were protein kinase 1 (AKT1), STAT3, JUN, interleukin-6 (IL-6), and mitogen-activated protein kinase 3 (MAPK3), which may be important targets for the treatment of lung adenocarcinoma with QSFZYL." (PMID 40642092, 2025).
atherosclerosis (22 papers, 2010 to 2026). A disease characterized by the build-up of fatty material and calcium deposition in the arterial wall resulting in partial or complete occlusion of the arterial lumen. "PPARA inhibits inflammatory reactions, one of the key factors involved in atherosclerosis, by stopping NFκB signalling, positively regulating IκBα, inhibiting JUN function, negatively regulating COX2, etc." (PMID 20937081, 2010). "Thus, KGs of NK cells for hawthorn's effects on the PVAT microenvironment of atherosclerosis were JUN, CXCR4, CD36, GNLY, and FABP4." (PMID 40824771, 2025). "JUN is involved in the lipid and atherosclerosis signaling pathways." (PMID 39534794, 2024). "In addition, some experiments have confirmed that shear force is involved in atherosclerosis via JNK signalling (JUN‐related pathway), which leads to the secretion of adhesion molecules (VCAM, ICAM, P‐selectin, E‐selectin, etc.)and the recruitment and migration of monocytes and macrophages." (PMID 40824771, 2025). "The mechanosensor Piezo1 and the downstream transcription factors c‐JUN and ETS1 regulate KDM5B expression, and KDM5B potentially contributed to atherosclerosis by regulating endothelial inflammation." (PMID 39643939, 2024). "There were six targets in the intersection with 137 candidate therapeutic targets of XFZYD, which included upregulated PTGS2, MMP9, and BCL2L1 and downregulated JUN, VEGFA, and CXCL2 in the atherosclerosis group." (PMID 33425996, 2020). "The targets of ATK2, IKBKB, RAF1, CHUK, TNF, JUN, and PRKCA were mainly involved in fluid shear stress and the atherosclerosis and PI3K-Akt signaling pathways." (PMID 29177114, 2017). "ATK2, IKBKB, RAF1, CHUK, TNF, JUN, and PRKCA were mainly involved in fluid shear stress and the atherosclerosis pathways, pathways in cancer, and the PI3K-Akt signaling pathway." (PMID 29177114, 2017).
Insulin resistance (22 papers, 2012 to 2025). Increased resistance towards insulin, that is, diminished effectiveness of insulin in reducing blood glucose levels. "Thirteen overlapping targets between the gut microbiota and insulin resistance were identified, among which IL6, JUN, and PPARG were recognized as hub genes." (PMID 40625623, 2025). "Genes with higher degree including VEGFA, PTGS2, JUN, MAPK8, and HSP90AA1 are hub genes of TwHF against DKD, which are involved in inflammation, insulin resistance, and lipid homeostasis." (PMID 33274236, 2020). "Examination of the KEGG pathway for NAFLD (hsa04932) demonstrated transcriptional dysregulation of mediators of insulin resistance (IRS2, P1K3R1, AKT1), steatohepatitis ( JUN, ERN1) and neutrophil infiltration and inflammation (CXCL8)." (PMID 29786565, 2018). "Gut microbiota metabolites may exert therapeutic effects on insulin resistance primarily through the targets IL6, JUN, and PPARG." (PMID 40625623, 2025).
lymphoma (22 papers, 2007 to 2026). A malignant (clonal) proliferation of B- lymphocytes or T- lymphocytes which involves the lymph nodes, bone marrow and/or extranodal sites. "Most intriguingly, the binding of JUN to BATF3 was also detectable in the cell lines of the BATF3-induced lymphomas." (PMID 29662618, 2018). "Western blot revealed a decrease in JUN expression in the fully formed lymphomas (from different but identical Smurf2T/T mice which the miRNA signature was measured from)." (PMID 28107482, 2017). "IGF1 and JUN were two key regulators of Ras cascade, and enhanced lymphoma development." (PMID 33107145, 2021). "We detected a significant enrichment of c-FOS, FOSL1, FOSL2, c-JUN, and BATF target genes in H3K27ac ChIP–seq peaks upregulated in ITK–SYK+PD-1− lymphoma cells compared to their premalignant ITK–SYK+PD-1+ counterparts." (PMID 37723306, 2023). "The 4‐circulating miRNA signature correlated with aberrant Ras protein signal transduction via IGF1 and JUN expression, and MDSC‐ and Th17 cell‐dependent lymphoma progression." (PMID 33107145, 2021).
colitis (21 papers, 2012 to 2025). Inflammation of the colon. "Meanwhile, transcription factors JUN, E2F1, and GATA2 have been reported to be closely related to the occurrence and development of colitis-associated tumors." (PMID 35733095, 2022). "Moreover, P. candolleana decreased the expression of IKBKB, JUN, CHUK, and TNF-α proteins, thus exerting anti-inflammatory and therapeutic effects on colitis." (PMID 38645561, 2024). "As an important mediator of oncogenic β-catenin signaling in the intestine, JUN is not only involved in inflammatory response and tumorigenesis but is also related to the inflammatory response in mice with LPS-induced macrophages and DSS-induced colitis." (PMID 35586697, 2022).
Alzheimer disease (20 papers, 2013 to 2026). A progressive, neurodegenerative disease characterized by loss of function and death of nerve cells in several areas of the brain leading to loss of cognitive function such as memory and language. "Here the authors demonstrate that dysregulation of the pioneer transcription factor c-JUN (AP-1) underlies aberrant transposable element mobilization, associated innate immune 2 response, and impaired neurogenesis in Alzheimer’s disease." (PMID 38049398, 2023). "Among the 29 TFs activated in male PD patients, ADNP, JUN, MBD3, PRDM14, and ESR1 have known associations with neurodegenerative disorders such as Alzheimer's disease, mental retardation, schizophrenia, and autism." (PMID 36414996, 2022). "It was found that the activation of the JUN proto-oncogen with increased expression of its product, protein c-Jun, occurs in neurodegenerative diseases (amyotrophic lateral sclerosis, Alzheimer’s disease)." (PMID 33445687, 2021). "PI3K/AKT signaling is necessary for the protection of cortical neurons, while activation of JNK/c-JUN signaling has been detected in the brain neurons in Alzheimer’s disease models." (PMID 28018176, 2016). "Additionally, elevated levels of the Jun Proto-Oncogene (JUN), the second-ranked hub gene in this module, have been observed in neurodegenerative conditions like Parkinson’s and Alzheimer’s disease." (PMID 38002524, 2023). "JUN is also the hub genes of ferroptosis-related genes of Alzheimer's disease." (PMID 36304416, 2022). "Decreased Fpn expression and abnormal iron deposition significantly increased NOX4, 4-HNE, and MDA levels in damaged astrocytes of cerebral cortex, and five hub genes (JUN, SLC2A1, TFRC, ALB, and NFE2L2) closely related to ferroptosis were identified in Alzheimer's disease (AD) patients." (PMID 36062196, 2022). "However, JUN, HDAC1, SP1, and STAT3 are also indispensable in the neuronal apoptosis mechanism of patients with Alzheimer's disease." (PMID 34992508, 2021).
myeloma (19 papers, 2012 to 2025). "Adaphostin as well as the proteasome inhibitor bortezomib were shown to induce apoptosis in multiple myeloma cells causing c-Abl cleavage and caspase activation in a JUN dependent manner." (PMID 38263136, 2024). "For example, it has been reported that c‐FOS/c‐JUN activity is altered in almost all MM patients and plays a major role in a transcriptional network associated with myeloma survival." (PMID 37581569, 2023). "Correspondingly, NFκB and JUN are known to regulate the expression of adhesion factors in multiple myeloma and B-cell lymphoma, respectively." (PMID 38598843, 2024). "In multiple myeloma cells, JUN overexpression induces cell death and growth inhibition by upregulation of the EGR1, which in turn downregulates Survivin and triggers caspase signaling." (PMID 35923847, 2022). "Interestingly improved outcome for the bortezomib treatment is associated with increased JUN or Egr1 expression, while JUN or EGR1 knockdown increases the resistance of myeloma cells against bortezomib." (PMID 35923847, 2022). "The results showed that KLF6, NR3C1, IRF7 and YY1 were all actively regulated in C0 IGLC3+ Myeloma Cells, C1 IGHA1+ Myeloma Cells, and JUN was actively regulated in C0 IGLC3+Myeloma Cells, C1 IGHA1+ Myeloma Cells and C3 IGHG4+ Myeloma Cells." (PMID 40406148, 2025). "Next, we further analyzed the regulatory activity of TOP5 TF of C0 IGLC3+ Myeloma cells, and we visualized the expression of KLF6, NR3C1, IRF7, YY1 and JUN in all cells and different tissue sources." (PMID 40406148, 2025). "Left panel: In multiple myeloma (MM), IKZF1/3 binds to the canonical IKZF‐binding motif CTTCC in a complex with c‐FOS/c‐JUN to activate the transcription of genes involved in the growth and survival of MM cells such as interferon regulatory factor 4 (IRF4) and SLAMF7." (PMID 37581569, 2023).
neuroblastoma (18 papers, 2009 to 2025). Neuroblastoma (NB) is the most common solid, extracranial childhood tumor. "More recently, HDAC inhibitors have been reported to transcriptionally suppress both c-JUN and FRA-1 and mechanistically block c-JUN/FRA-1 dimerization, affecting neuroblastoma cell growth." (PMID 29597249, 2018). "These two serine residues are located in the N-terminal transactivation domain of c-JUN and are known to be specific targets of JNK, further supporting the notion that ALK promotes neuroblastoma progress via JNK signaling." (PMID 27732954, 2016).
breast tumor (17 papers, 2010 to 2024). "To determine whether JUN expression is associated with BCLM we analyzed the correlation of JUN expression in primary breast tumors with patient prognosis." (PMID 29667003, 2019). "Expression of JUN has been observed in mitotic cells at the invasive front of breast tumors, indicating a potential role in both proliferation and invasion." (PMID 38935814, 2024). "Indeed, the JNK/JUN signaling pathway may promote the proliferation of some breast tumor cells in vitro." (PMID 29856313, 2018).
Stroke (17 papers, 2011 to 2025). Sudden impairment of blood flow to a part of the brain due to occlusion or rupture of an artery to the brain. "JUN, a member of the AP-1 family of transcription factors, also known as c-jun, is a downstream target of Jnk and is associated with apoptosis, inflammatory response, and reperfusion injury during stroke disease." (PMID 34603472, 2021). "Based on the 95 crossover genes identified, PPI network analysis uncovered six core genes including MMP9, MAPK3, PTGS2, JUN, IL1B and TNF likely linking the activity of luteolin to effective stroke control." (PMID 34898370, 2021). "In anti-stroke target analysis of the total group, the results showed that IL1B, IL8, JUN, MMP9 and PTGS2 were significantly up-regulated." (PMID 27672514, 2016).
triple-negative breast carcinoma (17 papers, 2014 to 2025). An invasive breast carcinoma which is negative for expression of estrogen receptor (ER), progesterone receptor (PR), and human epidermal growth factor receptor 2 (HER2). "We previously showed that high level of JUN and Fra-1 in triple negative breast cancer (TNBC) cells depends on ERK signaling pathway." (PMID 34244488, 2021).
Cerebral ischemia (16 papers, 2011 to 2024). Restriction of arterial blood supply to the brain associated with insufficient oxygenation to support the metabolic requirements of the tissue. "The genes CCL2, ICAM1, and JUN were identified as being associated with neurological disorders such as brain ischemia and schizophrenia." (PMID 39024368, 2024). "Consistently, our gene-disease analysis indicated that JUN is associated with mercury poisoning and brain ischemia, which are involved in neuronal death and result in the development of ASD." (PMID 35655651, 2022). "RELA, AKT1, JUN, PRKACA, PTGS2, RAF1 and CHUK were identified as four key targets associated with ischemic encephalopathy." (PMID 38285889, 2024).
squamous cell carcinoma (15 papers, 2010 to 2025). A carcinoma arising from squamous epithelial cells. "In squamous cell carcinoma, USP28 is strongly expressed and stabilizes the essential squamous transcription factor ΔNp63, together with important oncogenic factors, such as NOTCH1, c-MYC and c-JUN." (PMID 34685632, 2021).